CYP2C19 (cytochrome P450 family 2 subfamily C member 19)
Diseases named in the same sentence as CYP2C19 in open-access papers (continued):
Sharing a sentence is not in itself a finding about the gene and the disease.
Type 2 diabetes (5 papers, 2020 to 2026). "Nineteen CpG sites, annotated to genes involving drug metabolism, inflammation, lipid levels, and Type 2 diabetes, demonstrated non-linear associations with CYP2C19 metaboliser status." (PMID 42021410, 2026). "One study using a cocktail approach showed that CYP2B6, CYP2C19 and CYP3A activity decreased, CYP1A2 and CYP2C9 activity increased, and CYP2D6 and CYP2E1 activity was unaffected in type II diabetes (T2D)." (PMID 34867341, 2021). "Hence, the present study aims to characterize the activity of CYP1A2, CYP2B6, CYP2C9, CYP2C19, CYP2D6, CYP3A4/5, and P-glycoprotein (P-gp) pump in patients with type 2 diabetes (T2DM)." (PMID 32337164, 2020).
atherosclerosis (4 papers, 2022 to 2024). A disease characterized by the build-up of fatty material and calcium deposition in the arterial wall resulting in partial or complete occlusion of the arterial lumen. "Studies have shown that the CYP2C9 and CYP2C19 variant alleles are associated with a higher prevalence of atherosclerosis in cigarette smokers." (PMID 38791422, 2024).
bipolar disorder (4 papers, 2022 to 2023). A disorder of the brain that causes unusual shifts in mood, energy, activity levels and the ability to carry out day-to-day tasks. "Here, we investigate if CYP2C19 polymorphisms are associated with antidepressant treatment patterns and the risk of mania when antidepressants are used in bipolar disorder." (PMID 36333412, 2023). "To this end, we defined CYP2C19 metabolic phenotype by the rs4244285 and rs12248560 polymorphisms in a cohort of more than five thousand genotyped patients with bipolar disorder using information on dispensed medication from 2009 to 2017." (PMID 36333412, 2023). "We first tested if CYP2C19 metabolic phenotypes are associated with antidepressant response, side effects, and adverse events—as inferred from treatment discontinuation or switching to another antidepressants—in bipolar depression." (PMID 36333412, 2023). "In a large study of the impact of CYP2C19 metabolic phenotypes on antidepressant treatment of bipolar depression, we found an association between slower CYP2C19 metabolism and higher risk of treatment emergent mania, which is a step towards personalized risk assessments." (PMID 36333412, 2023). "In this study of more than 5000 patients with bipolar disorder, we found an association between CYP2C19 metabolic phenotypes and a manic episode within 3 months of starting treatment with either sertraline or the tricyclic antidepressants amitriptyline and clomipramine." (PMID 36333412, 2023). "Two single nucleotide polymorphisms (rs4244285 and rs12248560) were used to classify 5019 bipolar disorder patients into CYP2C19 metabolic phenotypes ranging from poor to ultra-rapid metabolizers." (PMID 36333412, 2023). "In conclusion, this is the first large scale study of the impact of CYP2C19 metabolic phenotypes on antidepressant treatment patterns and adverse events in bipolar disorder patients." (PMID 36333412, 2023). "This is the first large scale study on the importance of CYP2C19 metabolic phenotypes for antidepressant treatment patterns and adverse events in bipolar disorder patients." (PMID 36333412, 2023). "All things considered, our results show little impact of CYP2C19 metabolic phenotypes on early treatment persistence, treatment discontinuation, or switch to another antidepressant in bipolar disorder patients taking sertraline, citalopram, escitalopram, amitriptyline, and clomipramine." (PMID 36333412, 2023). "The aim of the present study was to test the effect of CYP2C19 metabolic phenotypes when antidepressants metabolized by CYP2C19 (citalopram, escitalopram, sertraline, amitriptyline, and clomipramine) are used by patients with bipolar disorder." (PMID 36333412, 2023).
colorectal cancer (4 papers, 2013 to 2024). A primary or metastatic malignant neoplasm that affects the colon or rectum. "Both CYP2C9 and CYP2C19 expressions are found to be critical in colorectal cancer." (PMID 31662772, 2019). "Therefore, in the present research work, CYP2C9, CYP3A, and CYP2C19 were selected to illustrate the effect of the CYP450 system on the progression of colorectal cancer." (PMID 31662772, 2019). "In T84 cells, which are derived from human colorectal carcinoma and thought to be a potential alternative to Caco-2 cells, the expression of CYP3A4 is controversial, while expressions of CYP2B6, CYP2C9, CYP2C19, and CYP2E1 are lacking." (PMID 34604364, 2021).
Hypoglycemia (4 papers, 2021 to 2025). A decreased concentration of glucose in the blood. "In the second one, omeprazole may augment the risk of hypoglycemia associated with gliclazide in most patients, as the oral antidiabetic is metabolised by CYP2C19, and omeprazole is an inhibitor of this enzyme." (PMID 35409994, 2022). "Since these drugs are metabolized by highly polymorphic enzymes such as CYP2C9 and CYP2C19, variability in enzyme function can lead to reduced drug efficacy and the occurrence of ADRs, including severe secondary hypoglycemia." (PMID 41011206, 2025). "The predicted results were corroborated by findings in patients with T2D which demonstrated over 3-fold higher odds of severe gliclazide-induced hypoglycemia in patients with CYP2C19 NM/RM/UM phenotype treated with omeprazole." (PMID 34063566, 2021). "However, when stratified by the CYP2C19 phenotypes, the co-treatment with PPIs was associated with severe hypoglycemia only in CYP2C19*2 non-carriers [OR = 2.34 (1.02–5.37), p = 0.044]." (PMID 34063566, 2021). "Although patient cohort with available genetic data was not large, we showed that patients with CYP2C19 NM/RM/UM phenotype treated with omeprazole had 3.26-fold (1.44–7.38) higher odds of severe hypoglycemia." (PMID 34063566, 2021).
ulcers (4 papers, 2012 to 2025). "Proton pump inhibitors (PPIs) are commonly used anti-ulcer agents, known to inhibit CYP2C19, leading to pharmacokinetic drug-drug interactions (DDIs)." (PMID 40415025, 2025). "This study permitted different kinds of PPI except for potassium-competitive acid blockers because a previous study confirmed that the healing speed of ESD-induced artificial ulcers was not affected by the CYP2C19 genotype." (PMID 36532761, 2022).
anemia (3 papers, 2024 to 2025). A reduction in the number of red blood cells, the amount of hemoglobin, and/or the volume of packed red blood cells. "It was found that the CYP2C19*2 polymorphic variant genotype was strongly linked to anemia, neutropenia, andthrombocytopenia after Adriamycin treatment." (PMID 40092865, 2024). "Qualitative hematological toxicity variables, including thrombocytopenia, leukopenia, neutropenia, lymphocytopenia, and anemia, were assessed at five different time points for their correlation with various alleles of the CYP2C19, ALDH3A1, SLC22A16, and ABCB1 genes." (PMID 40283974, 2025).
atrial fibrillation (3 papers, 2016 to 2026). A disorder characterized by an electrocardiographic finding of a supraventricular arrhythmia characterized by the replacement of consistent P waves by rapid oscillations or fibrillatory waves that vary in size, shape and timing and are accompanied by an irregular ventricular response. "This study aimed to evaluate the association of CYP2C19 and platelet reactivity (PR) with these risks, in atrial fibrillation (AF) patients undergoing PCI, treated with an oral anticoagulation (OAC) and clopidogrel." (PMID 42153956, 2026). "Recently, physicians have started implementing screening for the CYP2C19 variant as part of the medical decision making process when determining which drug to prescribe for atrial fibrillation." (PMID 27835996, 2016). "For example, a variant in P450 CYP2C19 reduces the amount of the active form of clopidogrel (a drug given when treating atrial fibrillation)." (PMID 27835996, 2016). "This is concerning since a subset of people with atrial fibrillation and the CYP2C19 variant may not achieve a therapeutic level of clopidogrel if prescribed the medication." (PMID 27835996, 2016).
congestive heart failure (3 papers, 2008 to 2021). Failure of the heart to pump a sufficient amount of blood to meet the needs of the body tissues, resulting in tissue congestion and edema. "An inverse relationship between plasma cytokine (TNF-α and IL-6) concentrations and CYP2C19 activity has been demonstrated in patients with congestive heart failure." (PMID 18854824, 2008). "In addition, an inverse relationship between CYP2C19 activity and plasma TNF-α or IL-6 concentrations has been reported in patients with congestive heart failure." (PMID 18854824, 2008). "In addition, one study showed that inflammatory markers were inversely correlated with CYP1A2 and CYP2C19 activity but not with CYP2D6 and CYP2E1 activity in patients with congestive heart failure." (PMID 34867341, 2021).
kidney transplant (3 papers, 2021 to 2025). A surgical procedure in which one or both kidneys from a donor are implanted into a recipient. "To assess whether genetic variations in CYP2D6 and CYP2C19 were associated with SAA and dry mouth, we compared genotype frequencies of those who had high SAA and dry mouth (n = 4) to those who had no high SAA and no dry mouth (n = 59)." (PMID 41347168, 2025).
leukopenia (3 papers, 2018 to 2025). "Both variants in CYP2C19 gene analyzed in this work, c.-806C>A (rs12248560; *17) and p.Pro227= (rs4244285; *2), correlated with leukopenia and recurrent neutropenia, respectively." (PMID 29507678, 2018). "The analysis revealed a significant increase in the mean leukopenia and lymphocytopenia grades after the fourth cycle of the AC regimen compared to baseline (point A) among patients carrying the CC genotype of the CYP2C19 gene (p < 0.05)." (PMID 40283974, 2025).
liver cirrhosis (3 papers, 2016 to 2021). "It is worthy of attention to the relationship between liver cirrhosis and the expression of CYP2C19." (PMID 34572712, 2021). "Moreover, previously published pharmacokinetic studies have demonstrated that clearance for CYP3A4/5 was markedly decreased in patients with either cirrhosis or severe alcoholic cirrhosis, while the clearance for CYP2C19 was also significantly reduced in patients with liver cirrhosis." (PMID 27086920, 2016). "No data on the in vivo clearance for CYPs in HCC patients was identified in a literature search, and only data regarding the clearance for CYP2C19 (67±40 ml/min) and CYP3A4/5 (319.49±154.42 ml/min) in liver cirrhosis were queried." (PMID 27086920, 2016). "Nevertheless, a subgroup of patients with decreased CYP2C19 activity (e.g., heritable poor metabolizers, patients with liver cirrhosis) or patients with absent CYP2C19 enzyme activity which is described in 3% of Caucasians and about 12–22% of Orientals might suffer from drug interactions." (PMID 30510930, 2018).
melanoma (3 papers, 2020 to 2022). A malignant, usually aggressive tumor composed of atypical, neoplastic melanocytes. "Such examples include the prescription of vemurafenib to melanoma patients carrying the BRAF V600E or warfarin and clopidogrel (Plavix) drugs prescribed for cardiovascular disease-treatment, the response of which is affected by genetic polymorphisms (VKORC1, CYP2C9 and CYP2C19 genes)." (PMID 35260588, 2022).
migraines (3 papers, 2021 to 2025). "While it has been shown that PPIs are associated with a higher risk of headaches and migraines, the specific association with CYP2C19 is still unclear." (PMID 40070570, 2025). "A recent study demonstrated that CYP2C19 phenotypes may modulate the association between PPIs and the development of migraines in patients treated with PPIs for medical comorbidities." (PMID 36355557, 2022). "Other aspects that might influence the effects of PPI on incident migraines may be related to cytochrome P450 2C19 (CYP2C19), the principal enzyme implicated in PPI metabolism." (PMID 36355557, 2022).
neutropenia (3 papers, 2018 to 2025). A decrease in the number of neutrophils found in the blood. "From the other hand, altered doxorubicin intake by the SLC22A16 variant (p.Asn104=) together with impaired drugs elimination (CYP2C19 p.Pro227=) and slower DNA damage repair with hematopoiesis disturbances (ERCC1 c.1510C>A) seemed to be the basis of recurrent neutropenia." (PMID 29507678, 2018).
peripheral arterial disease (3 papers, 2020 to 2024). A disorder of the arteries supplying the upper and lower extremity and the visceral organs. "Guo B, Tan Q, Guo D, Shi Z, Zhang C, Guo W. Patients carrying CYP2C19 loss of function alleles have a reduced response to clopidogrel therapy and a greater risk of in-stent restenosis after endovascular treatment of lower extremity peripheral arterial disease." (PMID 33111871, 2020).
pneumonia (3 papers, 2022 to 2025). An acute, acute and chronic, or chronic inflammation focally or diffusely affecting the lung parenchyma, caused by an infection in one or both of the lungs (by bacteria, viruses, fungi, or mycoplasma.). "Intriguingly, the risks of developing influenza and pneumonia are higher among CYP2C19 rapid and ultrarapid metabolizers regularly taking PPIs compared to other types of metabolizers." (PMID 39012339, 2024). "Reduced activities of CYP2C19 and CYP1A2 were associated with a higher risk of pneumonia." (PMID 40731880, 2025). "The risks of pneumonia were higher among CYP2C19 rapid and ultrarapid metabolizers." (PMID 39012339, 2024). "A prior study reported that poor metabolizer, one of the genotypes variabilities of CYP2C19, had higher blood levels of PPI and higher intragastric pH, which may be linked to great risk for pneumonia development." (PMID 35055393, 2022).
ST Elevation Myocardial Infarction (3 papers, 2020 to 2024). A myocardial infarction that produces elevation in the ST segments of the ECG. "Previous studies showed that adjusting thienopyridine treatment in patients after primary percutaneous coronary intervention for ST-Elevation Myocardial Infarction, according to the CYP2C19 genotype, can improve a patient’s outcome." (PMID 33370282, 2020). "In total, 92 patients with a confirmed diagnosis of ST-elevation myocardial infarction (STEMI) or non-ST-elevation myocardial infarction (NSTEMI) were sequenced for target regions within the CYP2C19 gene on the Illumina Miniseq system." (PMID 38791422, 2024).
Thrombocytopenia (3 papers, 2023 to 2025). A reduction in the number of circulating thrombocytes. "The mechanisms behind the association of CYP2C19 genotypes and increased risk of PPI-induced thrombocytopenia also require further exploration." (PMID 41216201, 2025). "We hypothesize that through the inhibition of CYP2B6, CYP2C9, CYP2C9, CYP2C19, and CYP3A4, Schisandra chinensis preparations increased the concentration and side effects of bupropion (thrombocytopenia and generalized arthralgia), amitriptyline (delirium), and fluoxetine (dysuria)." (PMID 37829299, 2023). "However, whether the CYP2C19 metabolizer status affects the occurrence of PPI-induced thrombocytopenia has not been reported, and none of the cases included in this study mentioned patients’ CYP2C19 genotyping." (PMID 41216201, 2025).
alcohol withdrawal syndrome (2 papers, 2023). "Given the highly polymorphic nature of the CYP2C19 gene, we reviewed the clinical impact of variants in the CYP2C19 gene on both the pharmacokinetics of diazepam and treatment outcomes related to the management of alcohol withdrawal syndrome." (PMID 36836519, 2023). "Moreover, several recent studies have examined the effects of CYP2C19 polymorphisms, particularly CYP2C19*17 and CYP2C19*2 variants, on the efficacy and safety of diazepam in individuals with alcohol withdrawal syndrome." (PMID 37239455, 2023).
alcoholism (2 papers, 2025 to 2026). "It means that hypertensive patients who are obese, have a history of alcoholism, and carry the CYP2C19 IM or PM phenotype need to be aware of the risk of developing CAD." (PMID 40715000, 2025). "In this study, CYP2C19 loss‐of‐function, BMI ≥ 24.0 kg/m2, and history of alcoholism were independent risk factors for CAD in hypertensive patients." (PMID 40715000, 2025). "In summary, CYP2C19 loss‐of‐function, BMI ≥ 24.0 kg/m2, and history of alcoholism were independent risk factors for CAD in hypertensive patients." (PMID 40715000, 2025). "It means that hypertensive patients who are obese, have a history of alcoholism, and carried the CYP2C19 IM or PM phenotype need to be aware of the risk of developing CAD." (PMID 40715000, 2025). "CYP2C19 loss‐of‐function, BMI ≥ 24.0 kg/m2, and history of alcoholism were independent risk factors for CAD in hypertensive patients." (PMID 40715000, 2025).
Cachexia (2 papers, 2008 to 2020). Severe weight loss, wasting of muscle, loss of appetite, and general debility related to a chronic disease. "The authors report a possible association between decreased CYP2C19 activity and low BMI due to cachexia." (PMID 32906709, 2020). "Alternatively, the overall increased protein catabolism in cachexia may play a more direct role in the compromised CYP2C19 activity." (PMID 18854824, 2008).
cerebral artery stenosis (2 papers, 2020 to 2021). A cerebrovascular disorder characterized by an abnormal narrowing of a cerebral artery. "In the current study, we acquired a conclusion that CYP2C19 polymorphisms was associated with clinical outcomes of clopidogrel therapy in patients who had received stent placement for cerebral artery stenosis in China." (PMID 33727661, 2021). "We investigated the effect of CYP2C19 polymorphisms on the clinical outcomes of clopidogrel therapy in patients after stenting procedure for cerebral artery stenosis in northeast China." (PMID 33727661, 2021). "Our study verifies that CYP2C19 *2 and *3 have significant impact on the clinical outcomes of clopidogrel therapy in patients with stenting procedure for cerebral artery stenosis in China." (PMID 33727661, 2021).
colon cancer (2 papers, 2021 to 2024). "Furthermore, molecular docking results indicated the stable binding connections between TQ/5-FU and the hub targets, i.e., MAP2K2, CASP3, PIK3CA, ESR1, CYP3A4, CYP2C19, and CYP2C9, suggesting that TQ, in combination with 5-FU, may treat colon cancer by modulating these hub targets." (PMID 39334689, 2024).
dementia (2 papers, 2020 to 2021). Loss of intellectual abilities interfering with an individual's social and occupational functions. "CYP2D6, CYP2C9, CYP2C19, and CYP3A4/5 geno-phenotypes are involved in the metabolism of over 90% of drugs currently used in patients with dementia, and only 20% of the population is an extensive metabolizer for this tetragenic cluster." (PMID 32357528, 2020).
Dravet syndrome (2 papers, 2019 to 2025). "It would have been of interest to measure Css, min levels of stiripentol given that many children with Dravet syndrome would also be taking this medication and stiripentol is metabolized by CYP2C19 and CYP3A4 isoenzymes." (PMID 31333569, 2019).
dyspepsia (2 papers, 2019 to 2023). An uncomfortable, often painful feeling in the stomach, resulting from impaired digestion. "Few previous studies reported relationship between H. pylori infection, CYP2C19 genotype and functional dyspepsia (FD) subtype." (PMID 31030500, 2019).
End Stage Liver Disease (2 papers, 2021). Final stage of a liver disease when the liver failure is irreversible and LIVER TRANSPLANTATION is needed. "The results of bivariate correlation analysis show that sex, the genotype of CYP2C19, daily dose, prothrombin time activity (PTA), international normalized ratio (INR), platelet, and Model for end-stage liver disease (MELD) score are significant factors." (PMID 34572712, 2021).